FOXJ1 (forkhead box J1)
Diseases named in the same sentence as FOXJ1 in open-access papers (continued):
Sharing a sentence is not in itself a finding about the gene and the disease.
Hydrocephalus (continued). "In this report, we describe two individuals with obstructive hydrocephalus internus and classic PCD clinical phenotypes who underwent targeted sequencing of FOXJ1." (PMID 34132502, 2021). "Five genes (TRIM71, SMARCC1, PTEN, PIK3C, MTOR) were found to be involved in syndromic forms of hydrocephalus, and three other genes (FMN2, FOXJ1 and PTCH1) to be responsible for severe hydrocephalus with AS stenosis." (PMID 34092257, 2021). "This study describes an inherent cellular plasticity of ECs as maintained by Foxj1 and IKK2 signaling, and shows resulting hydrocephalus when EC de-differentiation is triggered." (PMID 29695808, 2018). "Mice mutants lacking Foxj1 expression demonstrate the absence of cilia in airways, left–right axis defects, hydrocephalus, and infertility." (PMID 40348912, 2025). "The first generation of Ift140 cKO mice (Ift140flox/flox; FOXJ1-Cre±) did not exhibit gross abnormalities such as hydrocephalus, and they had normal left–right asymmetry." (PMID 40348912, 2025). "Examination of the MRI brain scans acquired in vivo revealed expansion of the cerebral ventricles in the FOXJ1-Cre;CEP164fl/fl with no obvious obstructions around the aqueduct consistent with communicating hydrocephalus when compared to the CEP164fl/fl mice." (PMID 35248089, 2022). "Having uncovered IKK2 regulation of EC Foxj1 stability, we next wanted to understand whether there are pathological conditions where IKK2 inhibition in vivo may induce hydrocephalus." (PMID 29695808, 2018). "Mechanistic analyses revealed a novel NF-κB-independent IKK2 activity stabilizing Foxj1 in mature ECs, and we found that known IKK2 inhibitors including viruses and growth factors robustly induced Foxj1 degradation, EC de-differentiation, and hydrocephalus." (PMID 29695808, 2018). "A majority of FOXJ1-Cre;CEP164fl/fl mice lived to adulthood without gross abnormalities, except for ~20% that succumbed to death due to severe hydrocephalus around weaning and another ~20% that exhibited mild hydrocephalus, which resolved itself later." (PMID 29244804, 2017). "Moreover, hydrocephalus is frequently observed across murine motile-cilia gene knockouts (e.g., DNAH5, DNAAF1) but remains uncommon in human PCD except in rare ciliogenesis disorders (e.g., CCNO, FOXJ1), underscoring a rodent–human discrepancy." (PMID 41477643, 2025). "The presence of Foxj1+ multiciliated ECs (not targeted by CreER) in tamoxifen-injected mutant mice showed that these phenotypic changes seen in Foxj1-deleted ECs was not induced by hydrocephalus." (PMID 29695808, 2018).
ciliopathy (15 papers, 2014 to 2025). A genetic disorder of the cellular cilia or the cilia anchoring structures, the basal bodies, or of ciliary function. "Clinically, this research is particularly relevant in the context of ciliopathies, such as de novo mutations in FOXJ1 resulting in motile ciliopathy characterised by hydrocephalus and airways defects." (PMID 38773599, 2024). "Remarkably, CFAP20 interacts with disease-causing proteins including: (i) ARL2BP, associated with RP, (ii) TBC1D32 and FOXJ1, related with ciliopathies, and (iii) LRRK2 and DICER1, involved in retinal degeneration in animal models." (PMID 35246562, 2022). "Early studies in animal models demonstrated FOXJ1 variants result in a motile ciliopathy with reduced ciliary numbers and mislocalized basal bodies in ciliated cells of the brain, airways, and embryonic left‐right nodal organizer." (PMID 34132502, 2021). "For example, the transcription factor FoxJ1 plays a crucial role in the constant maintenance of motile cilia, and mutation in FoxJ1 causes ciliopathy characterised by foetal hydrocephalus." (PMID 33874972, 2021). "In addition, Foxj1 targeted mutations elicit reductions in length and numbers of motile cilia in mice and zebrafish, while patient heterozygous FOXJ1 mutations cause ciliopathies associated with situs inversus and isolated CHD." (PMID 39175754, 2024). "However, the impaired drainage to the nasal cavity in the FOXJ1-Cre; CEP164fl/fl and p73−/− mice is more likely to be linked to the comorbidities associated with ciliopathy such as chronic rhinitis." (PMID 35248089, 2022). "Importantly, our study implies that downregulated cilia-related genes resulting from the mislocalization of FOXJ1 could be a pathway linked to the pathogenesis of motile ciliopathy." (PMID 37328841, 2023). "In FOXJ1-Cre;CEP164fl/fl mice, the endoturbinates were obliterated and filled with a substance characterized by homogeneous signal intensity likely representing accumulated mucus and infectious material associated with chronic rhinitis due to severe ciliopathy in the upper airways in this mutant." (PMID 35248089, 2022). "Therefore, determining the predicted regulatory network of FOXJ1, might in turn, help us to better understand ciliogenesis and ciliopathies associated with abnormal ciliary differentiation and function in humans." (PMID 30881373, 2019). "Dysfunction of the FOXJ1 (forkhead box J1) triggers autosomal dominant motile ciliopathies affecting many organ systems, including brain ventricles leading mainly to abnormal ventricular ciliary motility in CH." (PMID 39135208, 2024). "From these data we concluded that the p73−/− ciliopathy mice with lower body weight appeared to be more affected by the respiratory ciliopathy (i.e., chronic cough) compared to the FOXJ1-Cre;CEP164fl/fl mice." (PMID 35248089, 2022). "This hypothesis was not corroborated as we observed that the glymphatic transport was sustained in FOXJ1-Cre; CEP164fl/fl ciliopathy mice and was even increased in p73−/− mice." (PMID 35248089, 2022). "The observation of a smaller choroid plexus in p73−/− mice compared to the FOXJ1-Cre;CEP164fl/fl mice raise the possibility that CSF secretion differences might exist across the two ciliopathy mouse models and should be further explored in future in vivo studies." (PMID 35248089, 2022). "As our aim was to identify genes with potential relevance to ciliopathies, we removed Foxj1 targets without mammalian (mouse or human) orthologs, leaving 596 zebrafish genes, corresponding to 573 mammalian genes." (PMID 25139857, 2014).
asthma (8 papers, 2017 to 2024). "The deficiency of FTO caused the destabilization of FOXJ1 mRNA, which governs the expression of a critical transcription factor essential for ciliary function, consequently displaying potent asthma‐like features." (PMID 38706740, 2024). "The causality of aberrant FOXJ1 expression and the severity of NPs as well as the co-existence of AR and asthma cannot be disentangled with the present study design." (PMID 30459817, 2018). "By using immunofluorescence (IF) staining, we sought to unravel the association between the aberrant FOXJ1 localization with the severity of NPs and the presence of comorbidities (AR and asthma)." (PMID 30459817, 2018). "The process of FTO demethylation serves to stabilize FOXJ1 mRNA, promoting the development of motile cilia and subsequently suppressing the occurrence and advancement of asthma." (PMID 38706740, 2024). "We demonstrated a reduction in FOXJ1 gene expression in CR cells compared with parent asthma pBECs at terminal differentiation." (PMID 36041223, 2022). "Elevated FOXJ1 localization scores and down-regulation of FOXJ1 mRNA levels were observed in NPs with co-existing AR or asthma (all P < 0.05)." (PMID 30459817, 2018). "We interrogated if there were major differences between FOXJ1 localization score and the co-existence of AR or asthma in patients with NPs." (PMID 30459817, 2018). "The FOXJ1 localization score was significantly increased in both NPs with isolated AR, and NPs with isolated asthma (both P < 0.05)." (PMID 30459817, 2018). "In addition, these CR cells from donors with asthma express significantly lower FOXJ1 in comparison with “parent” pBECs at terminal differentiation." (PMID 36041223, 2022). "Aberrant localization of FOXJ1 correlates with the severity and co-existence of AR or asthma in patients with NPs, and might be a novel target for assessment and intervention in NPs." (PMID 30459817, 2018). "We sought to investigate whether aberrant FOXJ1 localizations correlate with the disease severity and the co-existence of allergic rhinitis (AR) or asthma in patients with nasal polyps (NPs)." (PMID 30459817, 2018). "Furthermore, the FOXJ1 mRNA expression levels were significantly down-regulated in NPs with isolated AR (n = 25), and NPs with isolated asthma (n = 20) (both P < 0.05)." (PMID 30459817, 2018). "Patients with FOXJ1 mislocalization might have greater severity of NPs and may more frequently develop co-existing AR or asthma." (PMID 30459817, 2018). "In summary, the aberrant localization of FOXJ1 correlates with the disease severity and the co-existence of AR and asthma in patients with NPs, which may provide novel candidate targets for more accurate clinical assessment and future treatment guidelines for NPs management." (PMID 30459817, 2018). "Compared with NPs without AR or asthma, the FOXJ1 localization score was significantly increased in patients with NPs who had more greater degree of allergy (G2-G4) (P < 0.05)." (PMID 30459817, 2018). "However, the FOXJ1 mRNA expression levels were markedly higher in NPs without AR or asthma (n = 32) than in control subjects (P = 0.035)." (PMID 30459817, 2018). "Therefore, our FOXJ1-Cre;CEP164fl/fl mouse model provides a powerful tool to study diseases of multicilia, such as PCD, and to further elucidate how defective multicilia contribute to the pathology of chronic respiratory diseases, such as cystic fibrosis, asthma, and COPD." (PMID 29244804, 2017).
primary ciliary dyskinesia (8 papers, 2013 to 2024). A rare, genetically heterogeneous, primarily respiratory disorder characterized by chronic upper and lower respiratory tract disease. "Enriched genes include dynein light chain roadblock-type 2 (Dynlrb2), a target of forkhead box J1 (FOXJ1) that regulates motile ciliogenesis, and radial spoke head 1 homolog (Rsph1) mutations are a cause of primary ciliary dyskinesia." (PMID 32298260, 2020). "Primary ciliary dyskinesia (PCD, ORPHA: 244) is predominantly a rare autosomal recessive disease, with some rare cases of X-linked and one gene proposed to be autosomal dominant (FOXJ1-PCD)." (PMID 36856967, 2023). "Studies have addressed whether mutations in the FOXJ1 gene could be linked to primary ciliary dyskinesia, although this hypothesis has not been supported." (PMID 23822649, 2013). "Primary ciliary dyskinesia (PCD(OMIM #244400)) is a rare genetic disorder most often inherited in an autosomal recessive and X-linked manner; however, recent studies have shown that autosomal dominant variants in the FOXJ1 gene also cause PCD." (PMID 34445527, 2021). "Although ciliation is restored after two weeks despite the lack of FOXJ1, an increased frequency of cilia with ultrastructural alterations indicative of secondary ciliary dyskinesia is observed." (PMID 35563514, 2022).
viral infection (7 papers, 2013 to 2024). "We next wanted to determine if surviving viral infection induced any physiological alterations to FOXJ1 + survivor cells." (PMID 30770807, 2019). "We were next interested in understanding how viral infection induced this population of phenotypically unique, FOXJ1 + survivor cells." (PMID 30770807, 2019). "Remarkably, we found that both viral infections and serum treatment can robustly induce ependymal Foxj1 degradation and EC de-differentiation." (PMID 29695808, 2018). "Although a mobilization of the basal cell pool was detected, the lack of FOXJ1+ cells suggests that at least some of the ciliated cells at 14 dpi could be redifferentiating cells that overcame viral infection." (PMID 35563514, 2022). "In line with this, we found mRNA levels of markers of epithelial cell differentiation to ciliated cells (transcription factor FOXJ1 and the ciliary apical structure protein SNTN) to be lower following co-infection with non-mucoid PA and HRV than after viral infection alone." (PMID 35265536, 2022).
breast carcinoma (6 papers, 2019 to 2025). "However, three previous studies analyzing the same TCGA dataset, searching for potential prognostic factors, have reported the expression of FOXJ1 mRNA as a favorable prognostic factor in breast cancer." (PMID 39936988, 2025). "With regard to DNA methylation expression levels, cg06807713, cg25721818, cg23384027, cg17869315, cg24087497 from NFE2; cg16861241, cg12284789, cg25051233 from FOXJ1 came up with the highest levels and significant prognostic values (likelihood ratio (LR) test P < 0.05) in breast cancer." (PMID 37596527, 2023). "Our study showed that higher expression of FOXJ1 was associated with better DFS in breast cancer, and FOXJ1 may be a good prognostic factor for the prognosis of breast cancer." (PMID 32977823, 2020). "ABCA3, CCL22, FOXJ1, IL1RN, and MAP2K6 may serve as good prognostic factors, while KCNIP3 and MRPL13 may be poor prognostic factors for the prognosis of breast cancer." (PMID 32977823, 2020). "Combined with our results, it was speculated that CCL22, FOXJ1, and IL1RN may play an important role in ameliorating the prognosis of breast cancer patients through involving in immune response." (PMID 32977823, 2020). "Moreover, future studies should analyze FOXJ1 expression and other markers of MCC differentiation in a large series of breast carcinomas, including all molecular subtypes, to better understand the biological and clinical significance of this specific type of cellular differentiation." (PMID 39936988, 2025). "Biomarkers including FOXJ1, CCL22, ABCA3 and IL1RN may be good prognostic factors in breast cancer." (PMID 36397112, 2022). "In conclusion, ABCA3, CCL22, FOXJ1, MAP2K6, and IL1RN may serve as good prognostic factors, while KCNIP3 and MRPL13 may be poor prognostic biomarkers to predict the recurrence and prognosis of breast cancer." (PMID 32977823, 2020).
colorectal cancer (5 papers, 2020 to 2022). A primary or metastatic malignant neoplasm that affects the colon or rectum. "The results suggest that increased FOXJ1 contributes to the progression of colorectal cancer, which might be associated with the promotion effect of β-catenin nuclear translocation, and it may be a novel therapeutic target in colorectal cancer." (PMID 32883271, 2020). "Overexpression of FOXJ1 enhanced the proliferation and progression of cancer cells of prostate cancer and colorectal cancer." (PMID 36397112, 2022). "In a colorectal cancer study, the overexpression of FOXJ1 significantly promoted nuclear translocation of β-catenin, an important factor in the Wnt-β-catenin pathway and in intestinal tumorigenesis." (PMID 34944845, 2021). "In a recent report, an increased expression of FOXJ1 associated with the clinical stage, metastasis of lymph node, and invasion depth in colon cancer suggest FOXJ1 is a tumor promoter in colorectal cancer." (PMID 32883271, 2020). "However, there are several instances of FOXJ1 overexpression in tumors, such as clear cell renal cell carcinoma and colorectal cancer, that merit further investigation." (PMID 34944845, 2021). "Forkhead box protein J1 (FOXJ1) is upregulated in bladder cancer and colorectal cancer but downregulated in ependymoma and choroid plexus tumors." (PMID 33564686, 2021).
ependymoma (5 papers, 2021 to 2023). A WHO grade II, slow growing tumor of children and young adults, usually located intraventricularly. "Decreased FOXJ1 expression and cilia formation in ependymomas and choroid plexus tumours are markers of poor prognosis and are therefore useful biomarkers for evaluating these tumours." (PMID 35292033, 2022). "The expression of RFX2 and FOXJ1 in ependymomas is higher than that in normal tissues and other brain tumors such as astrocytomas." (PMID 35087169, 2022). "Survival associations consistent with our HGSC results have been observed in gastric cancer, as well as ependymomas and choroid plexus tumours, where high expression of FOXJ1 is thought to be a marker of better tumour differentiation and a more favourable prognosis." (PMID 36323878, 2023). "Interestingly, FGFRi treatment resulted in induction of astroependymal-like signatures as well as FOXJ1 and RFX2, both factors associated with a more differentiated ependymal-like cell state in brain development and ependymoma." (PMID 34046693, 2021).
lung carcinoma (5 papers, 2012 to 2025). "Among the lung-specific TFs inactivated in lung cancer and precursor lesions, and which may be implicated in early causal pathways, it is worth highlighting the following:the TF FOXJ1 was found to be inactivated in LSCC, LCIS, and marginally so in buccal tissue of smokers." (PMID 29262847, 2017). "The unbiased discovery of the AHR pathway as well as pathways involved in hypoxia (HIF3A) and mucosa-mediated clearance of lung airways (FOXJ1), demonstrates the ability of SEPIRA to identify early and potentially causal pathways in lung cancer development." (PMID 29262847, 2017). "Interestingly, the top 5 most highly expressed SAE-enriched transcription factors all have previously been established as having a role in airway biology and/or lung cancer, including FOXJ1, ELF3, TRIM29, SOX2, and FOXA1." (PMID 22375630, 2012).
gastric cancer (4 papers, 2018 to 2023). A primary or metastatic malignant neoplasm involving the stomach. "However, FOXJ1 appears to play dual roles since lower expression of FOXJ1 is associated with worse prognosis of patients with gastric carcinoma." (PMID 30360388, 2018). "FOXJ1 promotes bladder cancer, prostate cancer, hepatocellular cancer, and gastric cancer growth, and metastasis." (PMID 35060926, 2022).
ovarian carcinoma (4 papers, 2015 to 2021). A malignant neoplasm originating from the surface ovarian epithelium. "NANOG1 overexpression in ovarian cancer cells has been shown to enhance migration capacity, which is accompanied by decreased E-cadherin, caveolin-1, FOXJ1, and FOXO1 expression." (PMID 26087476, 2015). "NANOG controls cell migration and invasion by regulating FOXJ1 expression in ovarian cancer." (PMID 34109184, 2021). "In addition, recent studies have suggested that FOXJ1 may be a tumor suppressor, which suppresses cell migration and invasion in ovarian cancer." (PMID 32977823, 2020). "Eight immune factors (IFT57, MAL, ANXA4, SCRN1, LTBR, KIFAP3, HSPA5, and LTN1) were positively correlated with poor prognosis of ovarian cancer, whereas six immune factors (PSMB9, FOXJ1, CTSH, MIF, CTSD, and PSMB8) were negatively correlated with poor prognosis of ovarian cancer." (PMID 34109184, 2021). "In ovarian cancer, stable knockdown of NANOG led to decreased cell proliferation, migration, and invasion, which were accompanied by increased expression of E-cadherin and FOX-related genes including FOXJ1, results consistent with our findings." (PMID 27588392, 2016).
cystic fibrosis (3 papers, 2017 to 2024). Autosomal recessive disorder caused by pathogenic variants in the CFTR gene (cystic fibrosis transmembrane conductance regulator), which encodes a chloride and bicarbonate channel expressed in epithelial cells, and follow the diagnosis criteria. "Curiously, all DTA+ populations, apart from DTA+_Foxj1+ cells, displayed increased levels of Cftr, a transmembrane conductance regulator that is mutated in cystic fibrosis." (PMID 38472236, 2024).